CD4 (CD4 molecule)
Diseases named in the same sentence as CD4 in open-access papers (continued):
Sharing a sentence is not in itself a finding about the gene and the disease.
tuberculosis (continued). "This could be due to both tuberculosis and HIV infection inducing immune activation in a similar pattern or due to the nature of HIV positive participants in this study where majority of them were at less advanced HIV infection stage as confirmed by their CD4 count." (PMID 24592945, 2014). "Incidence of tuberculosis was higher when subjects had CD4 cell count <200 cells/mm3; were not on antiretroviral therapy; in those who had, a body mass index <18.5 kg/m2, anemia (or were not tested for it), were illiterate or referred previous tuberculosis treatment at entry into the cohort." (PMID 23675515, 2013). "The absence of an association between CD4 cell count, prior or current HAART use, and certain medical conditions (e.g., tuberculosis) with malnutrition suggests that the effect of poverty on nutritional status in HIV may not necessarily be mediated by comorbidities." (PMID 23144941, 2012). "In fact, in addition to a recognized, direct role in protection against TB through their cytotoxic activity on M. tuberculosis-infected cells, CD8+ T cells specific for mycobacterial antigens can suppress IFN-γ production and proliferation by CD4+ T cells." (PMID 21603219, 2011). "HIV load, CD4 count, and markers of immune activation (CD38 and HLA-DR on CD4 and CD8 T cells) were measured prior to starting, during, and for 6 months after completion of standard 6 month anti-tuberculosis (TB) therapy in 38 HIV infected Ugandans with smear and culture confirmed pulmonary TB." (PMID 20179751, 2010). "Although human CD4 T cells have been shown to be important for protection against adult form of pulmonary tuberculosis, the role of IL-22-producing T cells in TB is not known." (PMID 20195465, 2010). "More recently, we reported that HMBPP activation of Vγ2Vδ2 T cells can antagonize IL-2-induced CD4+CD25+Foxp3+ T regulatory cells in mycobacterial infection, suggesting that Vγ2Vδ2 T cells may play a regulatory role as well in immune responses against tuberculosis." (PMID 20195465, 2010). "Although it is widely accepted that CD4 T cells play a critical role in the ability of humans and experimental animals to resist active M. tuberculosis infection, the contribution of CD8 T cells to natural or BCG-induced immunity against tuberculosis remains unclear." (PMID 19381260, 2009). "Four immediate arm children had new clinically diagnosed acid fast bacilli smear-negative pulmonary tuberculosis (TB) at a median time of 60 weeks (range 48 to 72), and a median CD4 of 28% (IQR 22 – 37) and 637 cells/mm3 (IQR 568 – 894)." (PMID 18957095, 2008). "PD-1, CTLA-4, TIM-3, LAG-3 and, TIGIT on both CD4+ and CD8+ T-lymphocytes in the peripheral blood of treatment-naïve individuals from four cohorts, including active pulmonary tuberculosis (TB), HIV-1 infection only, HIV-TB co-infected, and healthy volunteers from North India." (PMID 40872312, 2025). "Considering the natural history of TB and HIV, it is likely that both infections were present before enrolment, particularly among individuals with low CD4 counts; this severe immunosuppression could lead to a flare up of existing Mycobacterium tuberculosis infection." (PMID 37440476, 2023). "Furthermore, the pulmonary delivery of BCG, non-tuberculous mycobacteria and protein TB vaccines also induce CD4+ and CD8+ TRM in the lungs that contributes to protection against M. tuberculosis infection." (PMID 37896952, 2023). "Analysis of PBMC apoptosis before and after stimulation in each study group showed that, unlike those of tuberculosis, sarcoid monocytes were resistant to Mtb-HSP-induced apoptosis, and CD4+ T cell apoptosis was increased in SA patients." (PMID 36982159, 2023). "When a lack of IFN-γ is synthetized by CD4+ T cells, CD8+ T cells increase their production of IFN-γ, but it remains insufficient to prevent active tuberculosis." (PMID 37686061, 2023).
tuberculosis (continued). "By wave, over time, there was an increasingly higher prevalence of diagnosed infections with low recent CD4 cell counts <200 cells/μL, unsuppressed recent VL, no previous ART, ongoing tuberculosis or COPD." (PMID 37339333, 2023). "Patients were screened for tuberculosis (TB), nontuberculous mycobacteria (NTM), histoplasmosis, and cryptococcal disease, independently of their CD4 cell count." (PMID 33916153, 2021). "In addition, the TAM-TB assay, which evaluates the ratio of the median fluorescence intensity of CD27 in the whole CD4+ T-cell population to that of CD27 in the MTB-specific IFN-γ+ CD4+ T cells, has a vital role in distinguishing between tuberculosis in LTBI in adults and children." (PMID 34176483, 2021). "We evaluated the DICE clusters once again and asked how well the Burel 74-gene signature distinguishing CD4 memory T cell gene expression in latently Tuberculosis (TB) infected from non-infected individuals could be separated by the DICE gene clusters." (PMID 34613979, 2021). "In addition, we find M. tuberculosis–specific CD4+ T cells are highly enriched in the lung, including TB-specific IL-17+ cells, which are largely absent from the blood." (PMID 33848273, 2021). "Given the reported positive correlation between the CD8+ T-cell response against TB antigens and higher CD8+ T-cell responses in the context of recent exposure to M. tuberculosis, we postulated that the CD8+ response would be more sensitive to LTBI treatment compared with the CD4+ response." (PMID 32544206, 2020). "Large proportions of participants had normal BMI (60%), had CD4 count <200 cells/mm3 (47%), were WHO stage 1/2 (58%), did not have tuberculosis (93%), and did not initiate ART within 30 days of enrolment (54%)." (PMID 32128998, 2020). "The use of urinary LF-LAM should be prioritised in all HIV-positive patients (regardless of CD4 cell count and clinical condition) who presents to the emergency centre with WHO tuberculosis symptoms." (PMID 36325129, 2020). "The importance of both CD4+ and CD8+ T cells to survival after M. tuberculosis infection has been demonstrated in both the mouse and non-human primate model of tuberculosis." (PMID 32858811, 2020). "In the multivariable model, men (OR: 1.47, p = 0.021) had higher odds of misclassification when compared to women who initiated ART for non-PMTCT reasons (CD4, WHO stage, tuberculosis coinfection)." (PMID 32318534, 2020). "In this context, several studies assessed the frequencies of M. tuberculosis-specific CD4 T cells in individuals suffering from latent tuberculosis infection (LTBI) or TB coinfected or not with HIV in the presence or absence (12, –, 15) of conventional antiretroviral therapy (cART)." (PMID 30541853, 2019). "The overall message regarding those OI (tuberculosis and cryptococcosis) was, not to defer ART at low CD4 cell counts, unless patients are suffering from neurologic affection, especially cryptococcal meningitis." (PMID 31729999, 2019). "Although tuberculosis can also occur in PLHIV who are not severely immunocompromised, its incidence in our study decreased with both increased CD4 cell count and the time spent on ART." (PMID 30383836, 2018). "Mouse models have shown that CAF01 induces a Th1- and Th17-biased CD4 T cell response combined with a humoral immune response and confers protective immunity against tuberculosis (TB) in mice, guinea pig and non-human primate models when formulated with antigens from Mycobacterium tuberculosis." (PMID 30063728, 2018). "Conversely, tuberculosis can accelerate HIV infection, and HIV-infected patients co-infected with tuberculosis have shorter survival compared to age- and CD4-matched patients who are HIV-positive but not infected with M. tuberculosis." (PMID 29770360, 2018).
tuberculosis (continued). "Overall male patients were older, and presented with more advanced WHO stage, had lower body mass index (BMI) and median CD4 count; a higher proportion of male was started on efavirenz-based regimen due to concurrent tuberculosis (TB) treatment or being under investigation to rule out TB." (PMID 26642214, 2015). "The PrOMPT and REMEMBER studies aimed to evaluate empirical tuberculosis treatment among people with HIV and very low CD4 counts who screened negative for active tuberculosis at study entry." (PMID 25872501, 2015). "In 2012, approximately 8.6 million people developed active TB with 1.3 million deaths of whom 320,000 were HIV/TB co-infected, There is a mutual interaction between HIV-1 and tuberculosis, each aggravating the other by reducing CD4+ cells and enhancing inflammation and HIV-1 replication." (PMID 25272020, 2014). "Risk of becoming LTFU and death has also been attributed to a poor clinical status at ART initiation indicated by: a low CD4 count, a low body mass index, initiation of ART at World Health Organization (WHO) clinical stage 3 or 4, and/or tuberculosis (TB) co-infection." (PMID 25033285, 2014). "We excluded 161 pregnant women, 2286 patients co-infected with tuberculosis, 111 patients initiated on NVP with high CD4 counts and 452 patients without a baseline CD4 count, leaving 12,840 patients in the final cohort for analysis." (PMID 25361827, 2014). "Xpert negative tuberculosis cases were clinically similar to Xpert positives, including HIV status and CD4 count, and had similar treatment outcomes including mortality and time to antiretroviral treatment initiation." (PMID 23762367, 2013). "Among the subgroup of patients tested positive for HIV, not everyone had CD4 count, and therefore we were unable to fully account for the possible effect of advanced stage of HIV infection on the outcome of care for tuberculosis." (PMID 22894713, 2012). "In the metaanalysis of all 11 studies, study participants receiving ART were about one-third as likely to develop tuberculosis as study participants receiving no ART, irrespective of their CD4 count (HR 0.35)." (PMID 22911011, 2012). "In the present study, we found that without any stimulation, CD4+ T cells in pleural fluid cells (PFCs) from patients with TBP expressed significantly higher levels of CD69 than PBMCs from patients with tuberculosis (TB) or healthy donors." (PMID 21887301, 2011). "Receipt of D4T in the initial regimen was associated with female sex, earlier year of ART initiation, higher WHO stage, and lower CD4 levels at ART initiation and the absence of co-prevalent tuberculosis." (PMID 21955541, 2011). "Among those with active TB, one sample was unreadable due to artifacts and one sample was deemed "unresponsive to M. tuberculosis antigens" (CD4+ T-cell count: 154/mm3) because it tested negative to both selected RD1 peptides and intact proteins (used as positive control)." (PMID 18226199, 2008). "The incidence of tuberculosis for people with well-controlled HIV (viral load <50), like the majority of participants in this study, are likely to have higher CD4 counts and lower TB incidence, so there is likely no meaningful difference between these times to initiation." (PMID 39867372, 2025). "These proportions were higher among PLWH with a history of tuberculosis at baseline versus those without (4.8% vs 2.2%), a detectable (≥50 copies/ml) versus undetectable HIV viral load (4.7% vs 1.7%), and a baseline CD4 count <200 vs ≥200 cells/μl (3.5% vs 2.4%)." (PMID 39902315, 2025). "Therefore, we suggest that the development of and survival after active TB disease may be the driver of increased provirus load in circulating CD4+ T cells, rather than M. tuberculosis infection, per se." (PMID 39345793, 2024).
tuberculosis (continued). "Our controls were patients recently diagnosed with HIV who presented with severe opportunistic diseases, mainly involving the central nervous system (neurotoxoplasmosis and cryptococcosis) and tuberculosis; they were not on ART and had low CD4 counts and high viral load at the time of admission." (PMID 37368746, 2023). "In contrast to WHO 2021, which makes recommendations without taking CD4 + levels into account (tuberculosis at non-neurological site, start ART within 2 weeks; tuberculosis meningitis, start at 4–8 weeks), Malawi, Nigeria, and Uganda require a CD4 + count to define when to start ART." (PMID 37996881, 2023). "Since that time, tuberculosis incidence in the UK has decreased further; people with HIV are living longer and guidelines on the timing of cART have changed, with immediate rather than CD4+-guided start now recommended." (PMID 32501837, 2020). "However, the incidence of tuberculosis remains higher in HIV-1–infected persons despite ART (compared to those HIV-1 uninfected), regardless of the duration of ART or CD4 count." (PMID 31419285, 2020). "Patients with missing data on baseline laboratory indicators (CD4 level, hemoglobin, and HCV co-infection) were more likely to not start ART and to be LTFU, and missing information on the history of tuberculosis treatment was significantly related to not starting ART." (PMID 31237899, 2019). "We analyzed frequencies of antigen-specific CD4 and CD8 T cells expressing IFNγ, IL-2, TNF and/or IL-17 from adolescents or adults, with or without Mycobacterium tuberculosis (M. tb) infection, who received MVA85A, AERAS-402, H1:IC31, H56:IC31, M72/AS01E, ID93+GLA-SE or BCG." (PMID 30830940, 2019). "This study has demonstrated that the ITSDM could be used to both identify and address coverage gaps for national programs other than CD4, such as HIV viral load, tuberculosis and non-communicable diseases." (PMID 30473993, 2018). "Although the protective capacity of antigen-specific CD8+ T cells is difficult to distinguish among the dominant CD4+ T cell response in intact mice, T cell vaccination that elicited a robust TB10.4-specific CD8+ T cell response did not protect mice from tuberculosis." (PMID 26745507, 2016). "The lowest survival probabilities were observed for patients with a bed ridden functional status (13.25%), a history of tuberculosis treatment (50.86%), no disclosure of HIV status (52.41%), a baseline CD4 count <350 cells/μL (52.83%), and WHO stage IV disease (43.7%)." (PMID 27820957, 2016). "The STATIS trial compares, among people with no overt evidence of tuberculosis at study entry, empirical tuberculosis treatment to intensive investigation for tuberculosis among HIV-positive patients with a CD4 count under 100 cells/μL in Cambodia, Côte d’Ivoire, Uganda and Vietnam." (PMID 25872501, 2015). "In addition, the 2013 WHO guidelines for antiretroviral therapy provide the evidence-based recommendation that in subjects with active tuberculosis ART should be initiated as soon as possible, irrespective of CD4 count." (PMID 25391135, 2014). "The association between MTB bacteremia and 30-day mortality was similar after adjustment for confounders (CD4 count, absence of HAART, anti-tuberculosis therapy prior to hospitalization and serum albumin concentration) (adjusted HR 1.8, 95% CI 1.2–2.8, p = 0.003)." (PMID 23940557, 2013). "In contrast to the CD4+ effector functional subsets, CD4+ IL-2-only PPD- and RD1-peptide-specific cells (data not shown) were principally TCM in both active tuberculosis and latent tuberculosis infection and were therefore unaffected by tuberculosis disease stage." (PMID 23966657, 2013). "Is there a CD4+ and CD8+ immunity alteration in patients with pulmonary tuberculosis (TB) and diabetes (DM) that does not recover after antituberculosis treatment?" (PMID 37764989, 2023).
tuberculosis (continued). "According to the data presented in this study, CD4+ T-cell counts were lower in people living with HIV and TB than in people not infected with M. tuberculosis." (PMID 37606452, 2023). "In contrast, no significant between-country differences in median CD4 cell count at week 24 (p = 0.82), week 48 (p = 0.19), or percent change in CD4 cell count from baseline by week 24 or 48 of cART was observed among TB-HIV patients co-treated with rifampicin based anti-tuberculosis." (PMID 32116703, 2020). "In addition, enhanced IFN-mediated genes in the blood neutrophils and monocytes were detected, but not in CD4+ or CD8+ T cells, in patients with active phase of tuberculosis suggesting the role of monocytes and neutrophils in the Type I IFN-mediated pathogenesis of tuberculosis." (PMID 31801478, 2019). "Mathematical modeling studies based on data from sub-Saharan African countries have suggested that substantial declines in tuberculosis incidence could be achieved by initiating antiretroviral therapy as soon as HIV infection is known, without waiting for a threshold CD4 count to be reached." (PMID 24937804, 2014). "The molecular profiles of TCRBV in peripheral blood mononuclear cells (PBMCs) and their subpopulations (CD4+ and CD8+ T cells) from subjects with active tuberculosis (TB) or latent TB infection (LTBI) have not been well described." (PMID 24010943, 2013). "Although MVA85A boosting leads to strongly increased Ag85A specific, IFN-γ producing CD4+ T cells responses in BCG vaccines, protection against tuberculosis could not be increased by this boosting regimen in infants in a rural area near Cape Town, South Africa." (PMID 24146869, 2013). "There were various reasons for poor ART uptake that included failure to reach the ART centre, not getting CD4 counts done, having a CD4 count > 350 cells/uL in the case of pulmonary tuberculosis and not returning to the ART centre after starting TB treatment." (PMID 21931674, 2011). "In order to lessen the burden of TB in HIV patients, new HIV-positive TB patients should receive a TB regimen containing 6 months of rifampicin and should be put on ART regardless of CD4 count as soon as possible within the first 8 weeks of antituberculosis treatment." (PMID 32528737, 2020). "On the other hand, CD8+ T cells have a protective role in immunity against TB; they can recognize infected cells and produce cytokines such as TNF and IFN-γ, lyse infected cells, and kill Mycobacterium tuberculosis (MTB), though not as effectively as CD4+ T cells." (PMID 37764989, 2023). "For HIV-positive patients with active tuberculosis (TB) or hepatitis B, HIV-infected partners in serodiscordant couples, pregnant and breastfeeding women, and children younger than five years of age, ART is to begin immediately upon HIV diagnosis and irrespective of CD4 cell count or clinical stage." (PMID 24892694, 2014).